TRIM47 (tripartite motif containing 47)
Diseases named in the same sentence as TRIM47 in open-access papers (continued):
Sharing a sentence is not in itself a finding about the gene and the disease.
hepatocellular carcinoma (7 papers, 2022 to 2026). A malignant tumor that arises from hepatocytes. "TRIM47 expression in hepatocellular carcinoma (HCC) tissues was analyzed through public databases." (PMID 41460629, 2025). "However, the biological functions of TRIM47 and its regulatory mechanism in hepatocellular carcinoma (HCC) remain unexplored." (PMID 39567506, 2024). "To assess the relevance of TRIM47 in hepatocellular carcinoma (HCC), we first analyzed its expression using public proteomic and transcriptomic databases." (PMID 41460629, 2025).
prostate carcinoma (7 papers, 2022 to 2025). A carcinoma that arises from epithelial cells of the prostate gland. "On the other hand, the tripartite motif (TRIM) protein TRIM47 is significantly increased in prostate cancer compared to normal tissues." (PMID 36743211, 2023). "TRIM47 has been identified as a prognostic indicator for patients with prostate cancer and was significantly correlated with worse cancer-specific survival rates in multivariate regression analyses." (PMID 37516854, 2023). "It has been reported that TRIM47 is upregulated in astrocytoma, prostate cancer, and non-small cell lung cancer, and overexpression of TRIM47 promotes the malignant development of tumors." (PMID 36906594, 2023). "In terms of hormone-dependent cancers, we previously showed that TRIM47 is a poor prognostic factor for prostate cancer patients." (PMID 35954308, 2022). "Taken together, given its small size yet excellent predictive power, we concluded [AQP1, SEPT8, RBM17, TRIM47, VPS25] as a novel, practical biomarker panel for predicting response to 17-AAG treatment in prostate cancer." (PMID 36743211, 2023). "For example, increased expression of TRIM47 is a negative prognostic predictor and correlates with poor prognosis in human prostate cancer, non-small cell lung carcinoma, and gastric cancer." (PMID 36906594, 2023).
pancreatic cancer (6 papers, 2021 to 2025). "For instance, TRIM47 has been implicated in promoting tumor progression in colon and pancreatic cancer by degrading SMAD4 and FBP1." (PMID 38199981, 2024). "They found that TRIM47 expression was significantly upregulated along with the decrease of FBP1 expressions in pancreatic cancer patient tissues linking to a lower survival rate, which was also approved in pancreatic cancer cells as well." (PMID 40618019, 2025). "To identify potential downstream substrates of the E3 ubiquitin ligase TRIM47, we screened the literature and found that the ubiquitination of FBP1 by TRIM47 was involved in the carcinogenesis of pancreatic cancer." (PMID 40801794, 2025). "In pancreatic cancer, a recent study claimed that TRIM47 can accelerate aerobic glycolysis and promote tumor progression by regulating FBP1-associated ubiquitination." (PMID 40618019, 2025). "It appears that targeting on ubiquitination of the TRIM47/FBP1 axis might develop a novel approach to suppress the worseness of pancreatic cancer." (PMID 40618019, 2025). "In pancreatic cancer, TRIM47 could promote the aerobic glycolysis by interacting with and ubiquitination of fructose-1,6-bisphosphatase (FBP1)." (PMID 35004288, 2021). "In pancreatic cancer, TRIM47 can ubiquitinate fructose-1,6-diphosphatase (FBP1) and accelerate the degradation of FBP1, so as to promote the glycolysis and proliferation of pancreatic cancer cells." (PMID 37582735, 2023).
gastric cancer (5 papers, 2023 to 2025). A primary or metastatic malignant neoplasm involving the stomach. "TRIM47 was overexpressed in clinical gastric cancer tissues, which is linked to poor differentiation and advanced TNM stages (III/IV) by bioinformatics analysis." (PMID 39768197, 2024). "Thus, higher expression of TRIM47 is linked with poor survival in non-small cell lung cancer and gastric cancer." (PMID 41385185, 2025). "The promotive effect of TRIM47 on gastric cancer can be mediated by the NF-κB signaling pathway in vitro in experiments using AGS gastric cancer cell lines." (PMID 39768197, 2024). "In addition to TRIM31, TRIM47 promotes cell proliferation, invasion, and migration of gastric cancer cells." (PMID 41385185, 2025).
non-small cell lung carcinoma (5 papers, 2017 to 2025). A group of at least three distinct histological types of lung cancer, including non-small cell squamous cell carcinoma, adenocarcinoma, and large cell carcinoma. "TRIM47 was frequently overexpressed and positively correlated with poor prognosis in non‐small cell lung cancer." (PMID 40801794, 2025). "TRIM47 and TRIM27 have an oncogenic role in colorectal, prostate, oesophageal, ovarian and non-small cell lung cancer, promoting proliferation and metastasis." (PMID 33772100, 2021).
renal cell carcinoma (4 papers, 2021 to 2025). "The effects of TRIM47 knockdown and overexpression in renal cell carcinoma cells on cell proliferation, invasion and xenograft tumor growth in nude mice were analyzed." (PMID 33622324, 2021).
cholangiocarcinoma (3 papers, 2021 to 2025). A carcinoma that arises from the intrahepatic biliary tree (intrahepatic cholangiocarcinoma) or from the junction, or adjacent to the junction, of the right and left hepatic ducts (hilar cholangiocarcinoma). "The GEPIA online tool was utilized to analyze the relationship between TRIM47 expression and patient survival in cholangiocarcinoma." (PMID 41380966, 2025). "High levels of TRIM47 expression predict a poor prognosis and reduced disease-free survival within 60 months for patients diagnosed with cholangiocarcinoma." (PMID 41380966, 2025). "The results revealed that TRIM47 was an oncogene in most tumors like cholangiocarcinoma (CHOL), esophageal carcinoma (ESCA), liver hepatocellular carcinoma (LIHC), and lung adenocarcinoma (LUAD), but it was a tumor-suppressor gene in kidney chromophobe (KICH) and prostate adenocarcinoma (PRAD)." (PMID 33833824, 2021). "The expression of TRIM47 and CD163 in the cholangiocarcinoma patient samples from The Cancer Genome Atlas database was positively correlated." (PMID 41380966, 2025).
liver cancer (3 papers, 2022 to 2025). An epithelial or non-epithelial malignant neoplasm that arises from the liver. "Transcriptomic data from The Cancer Genome Atlas (TCGA) database further confirmed that the mRNA levels of TRIM47 were significantly higher in liver cancer tissues (n = 371) than in normal liver tissues (n = 50)." (PMID 41460629, 2025). "This is consistent with reports that TRIM47 promotes metastasis in liver cancer by activating the Wnt pathway." (PMID 40618019, 2025). "Therefore, we examined the effects of TRIM47 on the activation of these signaling pathways in liver cancer cells." (PMID 41460629, 2025).
astrocytoma (2 papers, 2023 to 2025). "Among them, TRIM47 is identified as overexpression in astrocytoma for the first time." (PMID 40618019, 2025). "TRIM47, a member of E3 ubiquitin ligase, was identified by serial analysis of gene expression (SAGE) in astrocytoma and codes for a novel ring finger B-box coiled-coil (RBCC) protein." (PMID 36906594, 2023).
ovarian carcinoma (2 papers, 2022 to 2025). A malignant neoplasm originating from the surface ovarian epithelium. "The results show that the level of TRIM47 mRNA in ovarian cancer specimens was significantly higher than that in normal tissues." (PMID 36288633, 2022). "The present study's findings demonstrate that by activating STAT3 signaling, TRIM47 functions as an oncogene in ovarian cancer." (PMID 36288633, 2022). "Next, the authors examined the effect of TRIM47 knockdown on ovarian cancer cell migration and invasion." (PMID 36288633, 2022). "The authors here report that TRIM47 knockdown suppressed proliferation and invasion and promoted apoptosis of ovarian cancer cells, whereas TRIM47 overexpression enhanced cell proliferation and invasion." (PMID 36288633, 2022). "Ovarian cancer cell xenograft assays demonstrated that TRIM47 knockdown significantly inhibited tumor growth." (PMID 36288633, 2022). "This study analyzed TRIM47 biological function in human ovarian cancer and yielded experimental evidence that TRIM47 upregulation in ovarian cancer promotes cell proliferation, migration, and invasion by activating STAT3." (PMID 36288633, 2022). "TRIM47 was knocked down and overexpressed in ovarian cancer cell lines SKOV3 and OVCAR3, and the effects on proliferation, clone formation, apoptosis, invasion, and growth of xenograft tumors in nude mice were determined." (PMID 36288633, 2022). "•TRIM47 promoted ovarian cancer cell proliferation and invasion via STAT3 signaling." (PMID 36288633, 2022). "This study aimed to investigate the biological roles of TRIM47 in ovarian cancer." (PMID 36288633, 2022). "•Knockdown of TRIM47 inhibited ovarian cancer cell migration and invasion." (PMID 36288633, 2022). "•Knockdown of TRIM47 suppressed proliferation of ovarian cancer cells." (PMID 36288633, 2022). "TRIM47 knockdown suppressed proliferation and encourages apoptosis of ovarian cancer cells." (PMID 36288633, 2022). "TRIM47 knockdown in ovarian cancer cells resulted in a substantial reduction in p-STAT3 levels." (PMID 36288633, 2022). "In addition, TRIM47 enhanced STAT3 phosphorylation, and the knockdown of STAT3 attenuated the oncogenic role of TRIM47 in ovarian cancer." (PMID 36288633, 2022). "However, STAT3 knockdown abolished these effects, suggesting that TRIM47 is an oncogenic factor in ovarian cancer that at least in part exerts its activity through STAT3." (PMID 36288633, 2022). "TRIM47, therefore, appears to be a potential target for ovarian cancer prevention and/or therapy." (PMID 36288633, 2022). "Additionally, flow cytometry and TUNEL assays both demonstrated that TRIM47 overexpression reduced ovarian cancer cell apoptosis." (PMID 36288633, 2022). "Similarly, TRIM47 knockdown suppressed ovarian cancer cell invasion, migration, and epithelial-mesenchymal transition." (PMID 36288633, 2022). "Although TCGA analysis revealed that TRIM47 was highly expressed in ovarian cancer, additional prospective clinical trials with a large population are still warranted to validate the upregulation of TRIM47 in ovarian cancer and evaluate its clinical significance." (PMID 36288633, 2022). "Here, the authors found that TRIM47 knockdown reduced STAT3 phosphorylation at Tyr705 in both cultured and xenografted ovarian cancer cells, followed by reduced expression of the STAT3 target genes MCL-1, MMP2, and c-MYC." (PMID 36288633, 2022). "The authors also used GEPIA to analyze the mRNA levels of TRIM47 and STAT3 target genes in ovarian cancer tissues." (PMID 36288633, 2022).
renal carcinoma (2 papers, 2021 to 2022). A carcinoma arising from the epithelium of the renal parenchyma or the renal pelvis. "The mRNA and protein levels of TRIM47 were higher in human renal cancer tissues than those in paired normal adjacent tissues." (PMID 35371994, 2022). "TRIM47 mRNA and protein levels in human renal cancer and paired normal adjacent tissues were detected by qRT-PCR and Western blot." (PMID 33622324, 2021).
Stroke (2 papers, 2019 to 2023). Sudden impairment of blood flow to a part of the brain due to occlusion or rupture of an artery to the brain. "TRIM47, however, has been shown to be specifically expressed in blood vessels in the brain, the damage and rupture of which can cause stroke and also correlates with dementia." (PMID 38115822, 2023). "Similarly to TRIM37, TRIM47 and TRIM62 (both class IV), are both upregulated and promote inflammation in the hippocampus in an ischemia/reperfusion (I/R) injury model of stroke." (PMID 38115822, 2023).
triple-negative breast carcinoma (2 papers, 2023 to 2025). An invasive breast carcinoma which is negative for expression of estrogen receptor (ER), progesterone receptor (PR), and human epidermal growth factor receptor 2 (HER2). "In the current study, we shown that overexpression of TRIM47 correlates with progression and poor prognosis in triple-negative breast cancer." (PMID 36906594, 2023). "By analyzing the copy number of TRIM47 gene in triple-negative breast cancer samples of TCGA database, we found that TRIM47 contains up to 41% gene amplification or mRNA high level in triple-negative breast cancer." (PMID 36906594, 2023). "In our current study, we demonstrate that overexpression of TRIM47 was significantly correlated with poor prognosis in triple-negative breast cancer." (PMID 36906594, 2023). "Analysis of 39 human triple-negative breast cancer tissue specimens using IHC analysis showed that TRIM47 expression was inverse correlated with the expression levels of BRCA1 (P = 0.021)." (PMID 36906594, 2023). "Strikingly, we found that overexpression of BRCA1 significantly reverse the effect of TRIM47 on Olaparib sensitive in triple-negative breast cancer." (PMID 36906594, 2023). "TRIM47 overexpression conferred Olaparib sensitive in triple-negative breast cancer cell lines, but inhibited TRIM47 conferred Olaparib resistance in triple-negative breast cancer cell lines, as determined by colony formation and Annexin V/PI assay, compared with vector-transformed cells." (PMID 36906594, 2023). "However, the transcription level of the GADD45 was significantly reversed by TRIM47 overexpression, and increase by inhibition of TRIM47 expression in triple-negative breast cancer cells." (PMID 36906594, 2023). "Importantly, the mRNA expression of TRIM47 was significantly overexpression in triple-negative breast cancer compared to non-triple-negative breast cancer." (PMID 36906594, 2023). "Taken together, these results indicate that TRIM47 conferred Olaparib sensitive of triple-negative breast cancer and BRCA1 inhibits TRIM47 overexpression induced Olaparib sensitive both in vitro and in vivo." (PMID 36906594, 2023). "Consistently, western blot assay showed that TRIM47 was inversely correlated with the expression levels of BRCA1 (r = −0.857, P < 0.001) in 10 freshly collected clinical triple-negative breast cancer samples." (PMID 36906594, 2023). "Collectively, these results support the notion that overexpression of TRIM47 reduces BRCA1 expression and ultimately leading to Olaparib sensitive in triple-negative breast cancer." (PMID 36906594, 2023). "The inverse correlation between TRIM47 expression and BRCA1 pathway was further determined in a gene set enrichment analysis (GSEA) of triple-negative breast cancer specimens." (PMID 36906594, 2023). "Furthermore, we found that overexpression of TRIM47 resulted in reduced expression and half-life of BRCA1 but inhibited TRIM47 expression induced expression and half-life of BRCA1 in triple-negative breast cancer cells." (PMID 36906594, 2023). "Therefore, we analysis the correlation between TRIM47 and BRCA1 in triple-negative breast cancer." (PMID 36906594, 2023).
viral infection (2 papers, 2021 to 2024). "Similarly, TRIM47 is involved in the innate immunity against viral infection and is associated with neuronal autophagy, while TRIM56 regulates replication of many viruses." (PMID 38731834, 2024). "We examined whether TRIM47 undergoes ubiquitination when Tim-3 is overexpressed, as TRIM25, an E3 ligase with a structure similar to TRIM47, undergoes ubiquitination during viral infection." (PMID 34110282, 2021).
anaplastic thyroid carcinoma (1 paper, 2025). "In this study, we demonstrated that TRIM47 suppression was e detected in thyroid carcinoma, especially anaplastic thyroid carcinoma." (PMID 40618019, 2025). "The molecular mechanism of TRIM47 involving lung metastasis was next carried out in vivo xenograft assay with anaplastic thyroid carcinoma THJ-29 T cells treatedTRIM47 silencing with Sh-TRIM47-#1." (PMID 40618019, 2025). "Western Blotting was used to detect the protein level of TRIM47 in human normal thyroid cell line (Nthy-ori 3–1), differentiated thyroid carcinoma (DTC) cell lines (BCPAP, FTD-133), and anaplastic thyroid carcinoma (ATC) cell lines (ATC-1, THJ-16 T, THJ-21 T and THJ-29 T)." (PMID 40618019, 2025).
astroglioma (1 paper, 2021). "TRIM47 has a RING structure and is reportedly defined as E3 ligase.TRIM47 was first determined to be overexpressed in astroglioma, which is located at 17q24-25." (PMID 33622324, 2021).
brain glioma (1 paper, 2021). A malignant glioma that involves the brain. "Unfortunately, it is still elusive towards TRIM47 expression, characteristic, and biological function in brain gliomas." (PMID 33833824, 2021).
Cerebral ischemia (1 paper, 2024). Restriction of arterial blood supply to the brain associated with insufficient oxygenation to support the metabolic requirements of the tissue. "Tripartite motif-containing protein 47 (TRIM47) functions as an E3 ubiquitin ligase and is involved in numerous biological processes, including tumorigenesis, cerebral ischemia/reperfusion injury, and endothelial inflammation." (PMID 38771644, 2024).
Cognitive impairment (1 paper, 2026). Abnormal cognition is characterized by deficits in thinking, reasoning, or remembering. "Trim47-deficient mice, which model the human genetic anomaly, exhibit major cognitive impairments, increased blood-brain barrier (BBB) permeability, and astrogliosis, without neuroinflammation." (PMID 41667829, 2026). "Treatment with the NRF2 activator tert-butylhydroquinone prevented BBB and cognitive impairment in Trim47-mutant mice." (PMID 41667829, 2026).
colorectal tumors (1 paper, 2019). "We found that levels of TRIM47 mRNA and protein were increased significantly in colorectal tumors compared with nontumor tissues and the increased levels were associated with advanced tumor stage and poor outcome." (PMID 30979374, 2019).
dementia (1 paper, 2026). Loss of intellectual abilities interfering with an individual's social and occupational functions. "By leveraging unique human proteomic data, we propose that modulation of the TRIM47/NRF2 pathway could predict an increased susceptibility to cSVD, suggesting that targeting this pathway may offer a promising therapeutic approach for vascular cognitive impairment and dementia." (PMID 41667829, 2026).
invasive breast carcinoma (1 paper, 2023). A carcinoma that infiltrates the breast parenchyma. "Interestingly, the TRIM47 gene is located at the 17q24-25 locus of chromosome 17, while chromosome 17 multibody mutation is frequently reported in invasive breast cancer." (PMID 36906594, 2023).
liver fibrosis (1 paper, 2024). "Some can play the same role in the face of the same disease, such as TRIM28 and TRIM38 in the progression of MAFLD and TRIM15 and TRIM47 in liver fibrosis." (PMID 39199424, 2024).
lung fibrosis (1 paper, 2025). "TRIM47 targets PPM1A for ubiquitination, leading to its degradation via the 26S proteasome complex, which in turn increases the phosphorylation of Smad2/3 and contributes to lung fibrosis." (PMID 40901482, 2025). "Inhibiting TRIM47 expression can suppress the expression of Vimentin, α-SMA, and CTGF protein, reduce Smad2/3 phosphorylation and hydroxyproline production, thereby mitigating pulmonary fibrosis." (PMID 40901482, 2025).